ANAPC10 (anaphase promoting complex subunit 10)
Description:
Component of the anaphase promoting complex/cyclosome (APC/C), a cell cycle-regulated E3 ubiquitin ligase that controls progression through the cell cycle. APC/C acts by mediating ubiquitination and subsequent degradation of target proteins: it mainly mediates the formation of 'Lys-11'-linked polyubiquitin chains and, to a lower extent, the formation of 'Lys-48'- and 'Lys-63'-linked polyubiquitin chains. APC/C catalyzes assembly of branched 'Lys-11'-/'Lys-48'-linked branched ubiquitin chains on target proteins. APC/C is activated by CDC20 in the metaphase/anaphase transition of cell cycle, targeting the degradation of cyclin B and securin. APC/C is regulated by the mitotic checkpoint complex (MCC), which inhibits APC/C and delays chromosome segregation.
Synonyms: APC10; DOC1; DKFZP564L0562
Tractability: PROTAC: ubiquitination databases record sites on it; its protein half-life has been measured.
Gene: Protein-coding gene on chromosome 4 (144,831,908 to 145,098,823, reverse strand). Ensembl gene ENSG00000164162.
Subcellular location (Human Protein Atlas): Nucleoplasm; Golgi apparatus
Pathways (Reactome):
Cell Cycle: APC-Cdc20 mediated degradation of Nek2A; APC/C:Cdc20 mediated degradation of Cyclin B; APC/C:Cdc20 mediated degradation of Securin; APC/C:Cdc20 mediated degradation of mitotic proteins; APC/C:Cdh1 mediated degradation of Cdc20 and other APC/C:Cdh1 targeted proteins in late mitosis/early G1; Autodegradation of Cdh1 by Cdh1:APC/C; Cdc20:Phospho-APC/C mediated degradation of Cyclin A; Conversion from APC/C:Cdc20 to APC/C:Cdh1 in late anaphase; Inactivation of APC/C via direct inhibition of the APC/C complex; Phosphorylation of the APC/C; Regulation of APC/C activators between G1/S and early anaphase; Separation of Sister Chromatids
DNA Replication: Assembly of the pre-replicative complex; CDK-mediated phosphorylation and removal of Cdc6
Cellular responses to stimuli: Senescence-Associated Secretory Phenotype (SASP)
Disease: Aberrant regulation of mitotic exit in cancer due to RB1 defects
Gene expression (Transcription): Transcriptional Regulation by VENTX
Immune System: Antigen processing: Ubiquitination & Proteasome degradation
Gene Ontology:
Molecular function: protein binding
Biological process: anaphase-promoting complex-dependent catabolic process; protein branched polyubiquitination; protein K11-linked ubiquitination; protein K48-linked ubiquitination; regulation of meiotic cell cycle; regulation of mitotic cell cycle; protein ubiquitination
Cellular component: anaphase-promoting complex; cytosol; nucleoplasm; cytoplasm
Genetic constraint (gnomAD): Loss-of-function variants: 3 observed, 8.99 expected, observed/expected ratio (o/e) 0.33, 90% interval 0.15 to 0.86. That is too few expected variants to judge how well the gene tolerates losing a copy. Missense variants: 114 observed, 137.31 expected, observed/expected ratio (o/e) 0.83, 90% interval 0.71 to 0.97. Synonymous variants: 44 observed, 42.84 expected, observed/expected ratio (o/e) 1.03, 90% interval 0.81 to 1.32.
Homologues: Orthologues: chimpanzee ANAPC10 (100% identical), dog ANAPC10 (100% identical), macaque ANAPC10 (100% identical), pig ANAPC10 (100% identical), guinea pig ANAPC10 (99% identical), mouse Anapc10 (99% identical), rabbit ANAPC10 (99% identical), rat Anapc10 (99% identical), tropical clawed frog anapc10 (94% identical), zebrafish anapc10 (91% identical), Drosophila melanogaster APC10 (57% identical), Caenorhabditis elegans Y48G1C.12 (41% identical), and 1 more.
Diseases named in the same sentence as ANAPC10 in open-access papers:
ANAPC10 is named in the same sentence as 9 diseases in open-access papers, as found by Europe PMC text mining. Sharing a sentence is not in itself a finding about the gene and the disease. The quoted sentences say what the papers report.
colorectal cancer (1 paper, 2020). A primary or metastatic malignant neoplasm that affects the colon or rectum. "Likewise, aberrant increases of APC10 and APC11 proteins, which are two subunits of the APC/C encoded by ANAPC10 and ANAPC11 genes, have been recently evidenced in non-small cell lung and colorectal cancer tissues; interestingly, inhibitors of APC/C activity are currently under investigation." (PMID 33585202, 2020).
non-small cell lung carcinoma (1 paper, 2025). A group of at least three distinct histological types of lung cancer, including non-small cell squamous cell carcinoma, adenocarcinoma, and large cell carcinoma. "Knockdown of ANAPC10 has been shown to downregulate glutamine metabolism-induced autophagy and effectively inhibit proliferation and migration of non-small cell lung cancer cells." (PMID 40080350, 2025).
ANAPC10 also shares sentences with these, for which no sentence is quoted: cancer (3 papers); breast carcinoma (1); colorectal tumors (1); lung carcinoma (1); sarcoidosis (1); thymoma (1); tumor (1).